NLRP3 (NLR family pyrin domain containing 3)
Diseases named in the same sentence as NLRP3 in open-access papers (continued):
Sharing a sentence is not in itself a finding about the gene and the disease.
osteosarcoma (continued). "We evaluated the role of each structural protein and p7 in NLRP3 inflammasome activation using the NLRP3 inflammasome reconstitution system in U2OS (human osteosarcoma) cells." (PMID 30811485, 2019). "Moreover, Combined the overexpression of HTR2B and knockdown of STAT1 can further suppresses osteosarcoma progression via NLRP3 inflammasome." (PMID 40387572, 2025). "Univariate analysis of NLRP3 expression and osteosarcoma patients survival." (PMID 34393801, 2021). "Multivariate analysis of NLRP3 expression and osteosarcoma patients survival." (PMID 34393801, 2021). "The inhibition of NLRP3 by CY-09 or gene knockdown significantly suppressed the cell proliferation, tumor formation, migration, invasion, induced cell apoptosis and G0/G1 cell cycle arrest in osteosarcoma." (PMID 34393801, 2021). "Similarly, NLRP3 knockdown also reduced the tumor weight and volume of osteosarcoma, as well as the Ki-67 expression in tumor." (PMID 34393801, 2021). "Individualized therapy targeting NLRP3 may serve as a modality to prevent tumor progression of osteosarcoma." (PMID 34393801, 2021). "In conclusion, NLRP3 may be regarded as an independent prognostic biomarker and a potential therapeutic target for osteosarcoma." (PMID 34393801, 2021). "Our in vivo results further confirmed that the blockage of NLRP3 could suppress the formation of xenografted tumors of osteosarcoma." (PMID 34393801, 2021). "The present study showed that the NLRP3 protein was overexpressed in osteosarcoma specimens and could be an independent biomarker for the poor clinical outcomes of osteosarcoma patients." (PMID 34393801, 2021). "In line with those former studies, our results demonstrated that knockdown of the NLRP3 gene could suppress the malignant progression of osteosarcoma." (PMID 34393801, 2021). "Furthermore, tumor formation assay was used to analyze the effect of NLRP3 on the growth of osteosarcoma in vivo." (PMID 34393801, 2021). "The results demonstrated that NLRP3 inhibitor prevented the progression of the cell cycle from G0/G1 to S phases, which may further inhibit the repair process of DNA damage in osteosarcoma cells." (PMID 34393801, 2021). "Therefore, high expression of NLRP3 protein may be considered as an independent prognostic biomarker for osteosarcoma." (PMID 34393801, 2021). "Suppression of NLRP3 protein by its targeted inhibitor CY-09 or knockdown of the NLRP3 gene could inhibit the cell proliferation, migration, invasion, promote apoptosis and G0/G1 cell cycle arrest in osteosarcoma cells in vitro via NLRP3/Caspase-1/GSDMD pathway." (PMID 34393801, 2021). "However, the real status of NLRP3 in self-antigen modification and upregulation in osteosarcoma carcinogenesis remains unclear." (PMID 34393801, 2021). "Moreover, NLRP3 suppression by the inhibitor of CY-09 or lentivirus-induced gene knockdown inhibited the cell proliferation, migration, invasion and promoted the cell apoptosis and G1 cell cycle arrest in osteosarcoma via targeting the inflammasome pathway." (PMID 34393801, 2021). "Therefore, NLRP3/Caspase-1/GSDMD pathway may be involved in NLRP3-induced carcinogenesis of osteosarcoma." (PMID 34393801, 2021). "The present results of the western blot revealed that the NLRP3 as well as caspase-1, GSDMD, IL-1β, and IL-18 proteins decreased after NLRP3 blockage in osteosarcoma." (PMID 34393801, 2021). "Additionally, NLRP3 may be regarded as an independent prognostic biomarker for osteosarcoma." (PMID 34393801, 2021). "The multivariate analysis further confirmed the independent prognostic value of NLRP3 protein overexpression for PFS (hazard ratio (HR) = 2.92, p = 0.002, C-index = 0.70) and OS (HR = 4.09, p = 0.017, C-index = 0.79) in osteosarcoma patients." (PMID 34393801, 2021). "Univariate and multivariate analyses were performed to assess the contribution of NLRP3 high expression to PFS and OS in osteosarcoma." (PMID 34393801, 2021).
osteosarcoma (continued). "Furthermore, NLRP3 protein was found to be independently related to short PFS and OS in osteosarcoma patients." (PMID 34393801, 2021). "In total, high expression of NLRP3 protein was found in 45.45% (25/55) of the osteosarcoma tissues whereas not in the osteochondroma tissues." (PMID 34393801, 2021). "However, the prognostic and therapeutic values of NLRP3 protein have not been fully analyzed in osteosarcoma." (PMID 34393801, 2021). "However, the effect of NLRP3 on osteosarcoma has not yet been well explored." (PMID 34393801, 2021).
periodic fever syndrome (11 papers, 2013 to 2025). Fevers of unknown etiology recurring over months or years. "Gain-of-function mutations in NLRP3 cause hereditary periodic fever syndromes that are collectively referred to as CAPS, and these patients are currently treated with biologics that target secreted IL-1." (PMID 31525186, 2019). "Furthermore, the NLRP3 mutation (associated with Cryopyrin Associated Periodic Fever Syndrome) was inconsistent with the patient’s phenotype and no further segregation was performed." (PMID 36926348, 2023). "The NLRP3 rs6672995 and rs4353135 CD risk alleles are associated with decreased LPS-induced IL-1 production, and with a decrease in baseline NLRP3 expression, respectively, unlike gain-of-function mutations associated with the NLRP3 hereditary periodic fever syndromes." (PMID 37504266, 2023).
pneumococcal meningitis (11 papers, 2013 to 2025). An acute purulent infection of the meninges and subarachnoid space caused by Streptococcus pneumoniae, most prevalent in children and adults over the age of 60. "In a murine model of pneumococcal meningitis using Streptococcus pneumoniae serotype 3, we examined bacterial titers, cytokine profiles and brain histology at 6 and 30 hours after inoculation in wild-type (WT), Asc and Nlrp3 deficient mice." (PMID 23902681, 2013). "Some studies in animals have explored the role of NLRP3 in bacterial meningitis: It has been reported that the NLRP3 inflammasome contributes to brain injury in pneumococcal meningitis." (PMID 35145923, 2021). "In contrast, a study on pneumococcal meningitis showed that mice with an active NLRP3 signaling have higher clinical scores, suggesting that NLRP3 activation contributes to brain injury." (PMID 33424869, 2020). "The role of the NLRP3 inflammasome and release of IL-1β have been shown also in pneumococcal meningitis suggesting the involvement of P2X7 receptors in this pathology." (PMID 30814932, 2019). "Although purinergic signaling is essential for NLRP3 inflammasome-dependent IL-1β secretion from macrophages in vitro, is seems to be dispensable under in vivo conditions, namely in pneumococcal meningitis." (PMID 28300164, 2017). "In conclusion, the results of the present study suggest that S. pneumoniae induces pyroptosis through NLRP3 inflammasome activation in murine microglia and in murine pneumococcal meningitis." (PMID 26683708, 2015). "Based on these findings, the results of present study suggest that pneumococcus-triggered pyroptosis of microglia is promoted by NLRP3 inflammasome activation and contributes to the pathology of pneumococcal meningitis." (PMID 26683708, 2015). "In a murine model of pneumococcal meningitis we examined the pathophysiological roles of two inflammasome proteins, NLRP3 (Nod-like receptor protein-3) and adaptor protein ASC (apoptosis-associated speck-like protein)." (PMID 23902681, 2013). "The more pronounced phenotype of the Asc−/− mice as compared to the Nlrp3−/− mice with pneumococcal meningitis can be explained by other, NLRP3 inflammasome independent, functions of ASC." (PMID 23902681, 2013). "In our murine model of pneumococcal meningitis, deficiency of inflammasome components ASC and NLRP3 led to decreased systemic inflammatory responses and bacterial outgrowth in the systemic compartment as compared with WT mice." (PMID 23902681, 2013). "On the other hand, NLRP3 mediated inflammation in pneumococcal meningitis also conferred damage to the host tissue and NLRP3 deficient mice show an improved clinical outcome due to decreased brain inflammation." (PMID 23666718, 2013). "In addition, it has been shown that NLRP3 inflammasome plays a central role in brain injury through ATP-dependent lysosomal cathepsin B release in pneumococcal meningitis." (PMID 26683708, 2015). "In addition, it has been reported that NLRP3 inflammasome contributes to brain injury in pneumococcal meningitis." (PMID 26683708, 2015). "Discrepancies in brain damage in Nlrp3−/− mice between our study and the previous study in experimental pneumococcal meningitis may be explained by the different pneumococcal serotypes used to establish meningitis between both models." (PMID 23902681, 2013). "Therefore, pneumococcal meningitis induced by S. pneumoniae may induce pyroptosis in brain by activating NLRP3." (PMID 39887961, 2025). "Furthermore, activation of the NLRP3-inflammasome has been shown to drive immunopathology in Bacillus cereus infection, where NLRP3-induced inflammation strongly enhances the mortality of infected mice and in pneumococcal meningitis, driven by IL-18 and IFN-γ." (PMID 35967403, 2022).
pneumococcal meningitis (continued). "Previous studies found that the inflammasome proteins NLRP3 and apoptosis-associated speck-like protein containing a CARD (ASC) play important roles in the regulation of the systemic inflammatory response and development of cerebral damage during pneumococcal meningitis." (PMID 35145923, 2021). "Our results implicate an important role for inflammasome proteins NLRP3 and ASC in the regulation of the systemic inflammatory response and the development of cerebral damage during pneumococcal meningitis, which may dependent on the pneumococcal serotype." (PMID 23902681, 2013).
pulpitis (11 papers, 2015 to 2026). Inflammation of the dental pulp. "In this study, we found that mitochondrial OS promotes NLRP3 inflammasome activation and pyroptosis in odontoblasts, which is the major cause of pulpitis." (PMID 37086012, 2023). "Collectively, these findings demonstrate that the NLRP3 inflammasome plays a central role in mediating pulpitis and accelerates the transition from reversible pulpal injury to chronic pulpitis and periapical inflammation." (PMID 41596738, 2026). "Previous studies have reported the link between hypoxic conditions and NLRP3 inflammasome-mediated pulpal inflammation in the progression of pulpitis." (PMID 39343901, 2024). "Previous studies have reported that activation of the NLRP3/CASP1 inflammasome pathway in HDPFs promotes the progression of pulpitis." (PMID 39343901, 2024). "We found the upregulation of HIF-1α accompanied by the activation of the NLRP3 inflammasome during the development from reversible to irreversible pulpitis, which indicated the link between hypoxic conditions and pulpal inflammation." (PMID 39343901, 2024). "The odontoblast layer stained positively for NLRP3 in pulpitis tissues compared with normal controls." (PMID 37086012, 2023). "Later, it was confirmed that the NLRP3 inflammasome is involved in the occurrence of dental pulp inflammation." (PMID 35052653, 2022). "They determined an upregulation of NLRP3 when reversible pulpitis evolved into irreversible pulpitis, and miR-223 was considered to be an inhibitor of this signaling pathway." (PMID 35052653, 2022). "Meanwhile, in pulpitis tissue, the protein level of NLRP3, cleaved caspase-1 and cleaved IL-1β, which also play a key role in inflammation and pyroptosis, was significantly increased." (PMID 34887391, 2021). "We analysed the presence, localization and quantity of NLRP3 and caspase-1 in healthy dental pulp and pulp showing reversible pulpitis or irreversible pulpitis." (PMID 25684031, 2015). "In conclusion, this report demonstrates that tissue with irreversible pulpitis contains more functional NLRP3/caspase-1 than healthy pulp and pulp with reversible pulpitis tissue." (PMID 25684031, 2015). "Our data show that NLRP3 gene and protein expression is greater in pulp with irreversible pulpitis than in normal pulp and pulp with reversible pulpitis." (PMID 25684031, 2015). "Here, we found that the NLRP3/caspase-1 inflammasome pathway can be activated in pulp tissues with irreversible pulpitis." (PMID 25684031, 2015). "We demonstrate that NLRP3 protein expression occurs to a greater extent in pulp tissue with irreversible pulpitis than in normal pulp tissue and in tissue with reversible pulpitis." (PMID 25684031, 2015). "The level of NLRP3 mRNA was higher in pulp with reversible or irreversible pulpitis than in normal pulp." (PMID 25684031, 2015). "NLRP3 was more strongly expressed in pulp with irreversible pulpitis than in normal pulp or pulp with reversible pulpitis." (PMID 25684031, 2015). "Furthermore, NLRP3 inflammasome is a critical regulator for immune reactions during pulpitis progression, which activates caspase-1 into cleaved-caspase-1." (PMID 40414936, 2025). "Furthermore, we simulated the caries-related pulpitis microenvironment and revealed that LPS and hypoxic conditions had synergistic effects in promoting the NLRP3/ASC/CASP1 inflammasome pathway activation via NF-κB signaling in HDPFs." (PMID 39343901, 2024). "This study aimed to investigate the role of HIF-1α in the regulation of NLRP3 inflammasome pathway via NF-κB signaling under hypoxic conditions with or without LPS in human dental pulp fibroblasts (HDPFs) during the progression of pulpitis." (PMID 39343901, 2024). "In addition, elevated MitoSOX levels were presented in pulpitis tissues, especially in the odontoblast layer, and this was positively correlated with NLRP3 expression." (PMID 37086012, 2023).
pulpitis (continued). "Furthermore, it was ascertained that the expression of NLRP3 in human dental fibroblasts varies in different degrees of periapical PD, showing higher NLRP3 levels in irreversible pulpitis, in contrast to reversible pulpitis." (PMID 35052653, 2022). "The expression of NLRP3, caspase-1 and IL-1β was analysed by the detection of the relevant protein and mRNA in normal pulp and in pulp with reversible pulpitis or irreversible pulpitis." (PMID 25684031, 2015). "However, in tissue showing irreversible pulpitis, the odontoblast layers were disrupted and dental pulp cells displayed extensive staining for NLRP3 and caspase-1." (PMID 25684031, 2015). "HIF-1α served as a positive regulator of NLRP3/ASC/CASP1 inflammasome pathway activation via NF-κB signaling in HDPFs in the sterile pulpal inflammation and caries-related pulpitis microenvironment." (PMID 39343901, 2024). "Pulpitis often occurs alongside inflammation, so we focused on differential expressed circRNAs related signaling pathways, including TNF, NF-κB, NLRP3 inflammasome, MAPK, and Wnt signaling pathways." (PMID 35786385, 2022). "Furthermore, in our studies on the mechanism of pulpitis, we demonstrated that AIM2 and NLRP3 inflammasomes are highly expressed in inflamed pulp tissues." (PMID 37250902, 2023).
SARS-CoV infection (11 papers, 2020 to 2023). "As the NLRP3 inflammasome is implicated in the pathogenesis of influenza and severe acute respiratory syndrome coronavirus (SARS-CoV) infection, the potential clinical efficacy of a KD on viral infection is drawing attention." (PMID 35215432, 2022). "Inhibition of miRNA-223-3p led to a significant increase in NLRP3 mRNA at 2 and 4 days p.i., thus confirming that NLRP3 was a target of miRNA-223-3p during SARS-CoV infection." (PMID 35229638, 2022). "NLRP3 is a member of the pathway, and its activation by Viroporin 3a seems to have an important effect on the pathogenesis of SARS-COV infection." (PMID 34394108, 2021). "Previous studies showed that viroporins promote NLRP3 inflammasome activation, in fact NLRP3 activation was observed following influenza A virus and SARS-CoV infections." (PMID 32867310, 2020). "In particular, SARS-CoV-2 nucleocapsid protein (N) is directly involved in the activation of the NLRP3 inflammasome triggering a cytokine “storm”, which may end with multi-organ dysfunction, severe acute respiratory syndrome (SARS), and death." (PMID 35159254, 2022). "When tested in the context of SARS-CoV infection, treatments targeting NLRP3 pathway components including NF-κB, inflammatory macrophages, and IFN-I all demonstrated significant efficacy despite unchanged viral titers their respective human, murine, macaque, and/or in vitro models." (PMID 32655582, 2020). "As a result of miRNA-223 inhibition, mRNA expression levels of NLRP3 inflammasome and pro-inflammatory chemokines CXCL10, CXCL2, and IL-1ß were increased, suggesting a contribution of miR-223-3p in vivo to limit excessive lung inflammation induced by SARS-CoV infection." (PMID 35229638, 2022).